TGM2 (transglutaminase 2)
Diseases named in the same sentence as TGM2 in open-access papers (continued):
Sharing a sentence is not in itself a finding about the gene and the disease.
endometrial cancer (6 papers, 2019 to 2025). Primary or metastatic malignant neoplasm involving the endometrium (mucous membrane that lines the endometrial cavity). "Furthermore, TGM2 levels were higher in the blood of patients with endometrial cancer." (PMID 36005579, 2022). "EpCAM, TGM2, HE4, CA-125, and IL-33 measured in serum samples from 42 patients with endometrial cancer concerning clinicopathological factors." (PMID 33014844, 2020). "Comparison of the levels of EpCAM, TGM2, IL-33, CA125, and HE4 in pre- and post-operated endometrial cancer patients." (PMID 33014844, 2020). "CD44, transglutaminase 2 (TGM2), and epithelial cell adhesion molecule (EpCAM) were identified as novel plasma markers for endometrial cancer diagnosis using the MAGPIX® System, which employs magnetic nanoparticles coated with antibodies and requires a tiny sample volume (25 μL)." (PMID 41440277, 2025).
invasive breast carcinoma (6 papers, 2012 to 2025). A carcinoma that infiltrates the breast parenchyma. "(a) TGM2 gene expression, measured with RNA sequencing, of normal, tumor, and metastatic tissue from breast invasive carcinoma patients." (PMID 36475545, 2022). "Consistent with our findings there is a significant correlation between IL-6 and TGM2 mRNA expression across the 1084 patient samples in the TCGA invasive breast cancer dataset." (PMID 35729402, 2022). "A possible association of intra-cellular TGM2 expression with a better prognosis in invasive breast cancer has not been reported previously and needs confirmation in independent data sets." (PMID 39516660, 2024). "(d) TGM2 co-expression correlation data for breast invasive carcinoma." (PMID 36475545, 2022).
osteoarthritis (6 papers, 2012 to 2023). A noninflammatory degenerative joint disease occurring chiefly in older persons, characterized by degeneration of the articular cartilage, hypertrophy of bone at the margins and changes in the synovial membrane. "The study enriches the understanding of TGM2/Wnt/β-catenin pathway in BMSCs, which may be an effective strategy for bone-associated diseases such as osteoarthritis, spinal cord injury, and cartilage injury." (PMID 36872331, 2023). "TGM2 is distributed in bone and cartilage and can induce the hypertrophic differentiation of joint chondrocytes and osteoarthritis formation." (PMID 36872331, 2023). "In addition, TGM2 has been reported to activate Wnt/β-catenin in osteoarthritis and vascular smooth muscle cells." (PMID 36872331, 2023).
ovarian tumor (6 papers, 2013 to 2025). "To strengthen our findings, we used the CIBERSORT algorithm to estimate B cell immune proportions in human ovarian tumor samples from The Cancer Genome Atlas (TCGA) with high and low TGM2 expression." (PMID 40777010, 2025). "We also found that human ovarian tumors with low TGM2 expression had an increased proportion of memory B cells." (PMID 40777010, 2025). "In the library prepared from ovarian tumor tissue, 5 clones with coding sequences were identified using the HMGB1 bait (C1QA, DAG1, RPL29, RSF1, TGM2), and 6 (COMMD1, MIEN1, PCBP1, TBC1D25, ZFR, ZNF428) were identified with the HMGB2 bait." (PMID 32867128, 2020).
periodontitis (6 papers, 2018 to 2025). An acute or chronic inflammatory process that affects the tissues that surround and support the teeth. "Furthermore, as several biomarkers (e.g. TGF-β1, transglutaminase 2, NLRP3) have been implicated in the pathogenesis of periodontitis, it would be of interest to evaluate the effects of the test oral rinse on these early biomarkers." (PMID 36324127, 2022). "The ubiquitously expressed transglutaminase 2 (TG2) plays a crucial role in P. gingivalis adherence to host cells 6, with periodontitis being its sole known clinical manifestation in situ." (PMID 40386394, 2025).
pterygium (6 papers, 2009 to 2022). A wedge-shaped fibrovascular lesion arising from the bulbar conjunctiva and extending to the cornea. "A recent paper has shown that pterygium presents aberrant DNA methylation patterns in regions close to matrix remodelling genes such as TGM-2, MMP-2 and CD24." (PMID 22724003, 2012). "Here, we report for the first time the role of methylation in the pathogenesis of pterygium, by profiling the methylation status of TGM-2, MMP-2, and CD24 gene promoters and the effect of methylation in cultured ocular surface cells." (PMID 21359202, 2011). "TGM-2 transcript was downregulated by 0.42±0.03 fold (p<0.05) in pterygium relative to the conjunctiva." (PMID 21359202, 2011). "In our study, we found that critical CpG islands associated with the MMP-2 and CD24 genes were demethylated in pterygium, whereas TGM-2 gene sequences were over-methylated." (PMID 21359202, 2011). "Many other known functions of TGM-2 in wound healing that may explain pterygium formation have been reported, including effects on myofibroblasts." (PMID 21359202, 2011). "TGM-2 protein level was relatively lower in the pterygium compared to the conjunctival tissue." (PMID 21359202, 2011). "Immunofluorescent staining detected the presence of TGM-2, MMP-2, and CD24 in human conjunctiva and pterygium tissue." (PMID 21359202, 2011). "The methylation status at the promoters of TGM-2, MMP-2, and CD24 genes was significantly different between pterygium and uninvolved conjunctiva samples in at least one CpG unit." (PMID 21359202, 2011). "We have previously investigated the genes specifically involved in wound healing mechanisms such as TGM-2, MMP-2, and CD24 in pterygium." (PMID 21359202, 2011). "TGM-2, MMP-2, and CD24 gene transcripts were detected in conjunctiva and pterygium tissues." (PMID 21359202, 2011). "Methylation levels of TGM-2, MMP-2, and CD24 in pterygium and conjunctiva." (PMID 21359202, 2011).
schizophrenia (6 papers, 2012 to 2024). A major psychotic disorder characterized by abnormalities in the perception or expression of reality. "The rs7270785–rs4811528 haplotypes showed the strongest association with schizophrenia, and the authors suggested that the TGM2 gene might be involved in schizophrenia in the British population." (PMID 33422029, 2021).
vitamin D deficiency (6 papers, 2018 to 2025). A nutritional condition produced by a deficiency of VITAMIN D in the diet, insufficient production of vitamin D in the skin, inadequate absorption of vitamin D from the diet, or abnormal conversion of vitamin D to its bioactive metabolites. "To summarize, the present results suggest that in HIV+ subjects, vitamin D deficiency may be associated with changes in expression of TGM2 as well as other markers of inflammation and autophagy, resulting in immune cell dysfunction." (PMID 33066266, 2020).
acute promyelocytic leukemia (5 papers, 2016 to 2025). An aggressive form of acute myeloid leukemia (AML), characterized by arrest of leukocyte differentiation at the promyelocyte stage, due to a specific chromosomal translocation t(15;17) in myeloid cells. "In the NB4 WT acute promyelocytic leukemia cell line, ATRA treatment induces the maturation of cells into neutrophil granulocytes, resulting in the expression of multiple genes, including transglutaminase 2 (TG2), which is not typically expressed in healthy neutrophil granulocytes." (PMID 41184249, 2025).
colitis (5 papers, 2014 to 2025). Inflammation of the colon. "TGM2 was recently identified as a novel marker of epithelial responses in experimental and human colitis." (PMID 40386941, 2025). "The intervention of TCA on colitis mice can improve the inflammatory response by regulating the expression of the TGM2 gene." (PMID 41009970, 2025). "The intervention of TCA on colitis mice could improve the inflammatory response by regulating the expression of the TGM2 gene." (PMID 41009970, 2025).
depression (5 papers, 2013 to 2025). "A study found an increase in TGM2 expression in both chronic stress-induced depressive-like behavior in mouse model of depression and in depressed suicide subjects." (PMID 39254383, 2024). "Although there is evidence highlighting TGM2's critical role in depression, the mechanism by which stress leads to elevated TGM2 expression remains unclear." (PMID 39254383, 2024).
dermatitis (5 papers, 2013 to 2023). An inflammatory process affecting the skin. "Most notably, several RAR target genes involved in retinoid signaling were induced in allergen-induced dermatitis, whereas expression of RAR targets which are not implicated in retinoid signaling (Krt4, Rarres2, Tgm2) was not significantly altered." (PMID 23977003, 2013).
Infertility (5 papers, 2019 to 2025). "Screening for undiagnosed CeD among infertile individuals was primarily conducted using serological tests for antibodies against transglutaminase 2 (TGA), endomysium (EMA), and/or gliadin (AGA)." (PMID 40362884, 2025).
lymph node metastasis (5 papers, 2011 to 2023). "Multivariate analysis further demonstrated strong TGM2 expression (HR 15.87, p = 0.021) and lymph node metastasis (HR 13.16, p = 0.021) as independent predictors for tumor relapse." (PMID 37443286, 2023). "TGM2 was overexpressed in PTC, correlating positively with exthyroidal extension and lymph node metastasis." (PMID 33738254, 2021). "Primary tumor site, T stage, overall stage, lymph-node metastasis, BNIP3 expression and TGM2 expression were significant prognostic factors for OS in univariate analysis." (PMID 22458929, 2012). "This study indicates that lymph-node metastasis, BNIP3 expression and TGM2 expression are independent prognostic factors in laryngeal SCC patients receiving postoperative radiotherapy." (PMID 22458929, 2012). "Univariate analysis revealed following factors as significant negative predictors for DFS: lymph node metastasis (HR 3.291, p = 0.001), UICC stage III (HR 9.446, p = 0.002), Kras mutation (HR 8.938, p < 0.001) and strong TGM2 expression (HR 10.396, p < 0.001)." (PMID 37443286, 2023).
meningioma (5 papers, 2012 to 2024). A generally slow growing tumor attached to the dura mater. "Inhibition of TGM2 function by siRNA or cystamine induced meningioma cell death, which was associated with reduced AKT phosphorylation and caspase-3 activation." (PMID 25247996, 2014). "Since the TGM2 expression was high in meningiomas and associated with the aggressive tumor behavior, we reasoned that TGM2 inhibition might be a therapeutic target for meningioma." (PMID 25247996, 2014). "Importantly, the TGM2 expression level was associated with increasing WHO malignancy grade as well as meningioma recurrence." (PMID 25247996, 2014). "Treatment of meningioma cells with 5 nM siRNA decreased TGM2 mRNA expression by 80–90% 2 days after transfection by quantitative RT-PCR and resulted in a 30% reduction in cell survival." (PMID 25247996, 2014). "Compared with the arachnoid membranes, TGM2 gene expression was 11.33-fold higher in meningiomas (p = 0.001429; FDR p = 0.034055289)." (PMID 25247996, 2014). "The microarray analysis and immunohistochemical staining revealed that transglutaminase 2 (TGM2) expression was increased in higher-grade meningiomas and in recurrent tumors." (PMID 25247996, 2014). "Collectively, these findings suggest that TGM2 expression increases as a function of malignancy grade and tumor recurrence and that inhibition of TGM2 reduces meningioma cell growth." (PMID 25247996, 2014). "For grade I meningioma, high TGM2 expression (>50%) was observed in those with recurrence, while benign tumors had low TGM2 expression, suggesting that TGM2 expression may induce more aggressive tumor behavior." (PMID 25247996, 2014). "We also demonstrated that inhibition of TGM2 decreased meningioma cell growth." (PMID 25247996, 2014). "We also demonstrated that inhibition of TGM2 reduces meningioma cell growth." (PMID 25247996, 2014). "Furthermore, TGM2 inhibition by siRNA induced meningioma cell apoptosis (TUNEL + cells)." (PMID 25247996, 2014). "Abundant TGM2 expression (defined by >50% TGM2 immunopositive cells) was detected in all grade II and III meningiomas." (PMID 25247996, 2014). "Using this approach, increased transglutaminase 2 (TGM2) expression was observed, which was subsequently validated in an independent set of 82 meningiomas by immunohistochemistry." (PMID 25247996, 2014).
mesothelioma (5 papers, 2018 to 2025). A usually malignant and aggressive neoplasm of the mesothelium which is often associated with exposure to asbestos. "TGM2 plays a role in tumor formation and generates a stem-cell-like phenotype in mesothelioma." (PMID 37345150, 2023).
periodontal disease (5 papers, 2019 to 2022). "Proinflammatory mediators expressed in the rheumatoid synovium such as IL-6, TNF-α, transglutaminase 2, and inflammasome Nlrp3 have also been detected in saliva and serve as biomarkers for periodontal disease." (PMID 36506787, 2022). "For example, Matarese G demonstrated that transglutaminase 2 (TG2) may be involved in the molecular mechanism of inflammatory response in periodontal disease." (PMID 36076176, 2022). "Moreover, transglutaminase 2 (TG2), a protein cross-linking enzyme according to Matarese and Curro, has showed a positive correlation between TG2 and RANKL/OPG mRNA ratio, suggesting that TG2 may be involved in molecular mechanisms of inflammatory response occurring in periodontal disease." (PMID 36438901, 2022). "High levels of nuclear factor-kappa B (NF-κB), transglutaminase 2 (TG2) and several inflammatory mediators, including IL-1, IL-6, TNF-α, and prostaglandin E2 are produced in periodontal diseases." (PMID 31878036, 2019).
Stroke (5 papers, 2011 to 2023). Sudden impairment of blood flow to a part of the brain due to occlusion or rupture of an artery to the brain. "TGM2 is a multifunctional, scaffolding, calcium-dependent enzyme that is expressed at low levels in the brain but is strongly induced after stroke injury." (PMID 26438564, 2015).
cystinosis (4 papers, 2019 to 2023). Cystinosis is a metabolic disease characterized by an accumulation of cystine inside the lysosomes, causing damage in different organs and tissues, particularly in the kidneys and eyes. "The commercially available ocular solution for treatment of ocular manifestations of Cystinosis, Cystaran®, contains the TGM2 inhibitor cysteamine hydrochloride (CH)." (PMID 36470430, 2023).
endometriosis (4 papers, 2014 to 2024). The growth of functional endometrial tissue in anatomic sites outside the uterine body. "The levels of GRP78 and PPA1 expression were higher in the GnRHa- (untreated) group compared with the GnRHa + (GnRHa-treated) group (P <0.05), while EFHA2 and TGM2 expression significantly increased in endometriosis patients after GnRHa treatment (P <0.05)." (PMID 25367189, 2014). "Concentration of seven analytes (ALDH1A, CA9, CD44, hepsin, midkine, TGM2, and kallikrein-6) differed in endometriosis samples as compared to control samples and levels of five markers (ALDH1A, CA9, CD44, hepsin, and midkine) were different between endometriosis and EC samples." (PMID 31035965, 2019). "It was also found that a regression model consisting of CD44 and TGM2 discriminated endometriosis from control samples with high accuracy (AUC 0.98, 95% CI 0.85–1.00, p < 0.001), however this result needs to be considered as preliminary due to the small number of endometriosis samples." (PMID 31035965, 2019).
Insulin resistance (4 papers, 2015 to 2025). Increased resistance towards insulin, that is, diminished effectiveness of insulin in reducing blood glucose levels. "In vivo Tgm2 silencing in CD11b+ cells in HFD mice resulted in pro-inflammation in eWAT and serum, and increased adiposity and insulin resistance, suggesting that TGM2 + ATMs possess an anti-inflammatory role in obesity that is insufficient to reverse obesity-induced inflammation." (PMID 40467990, 2025).
multiple myeloma (4 papers, 2008 to 2024). "Together, the expression of adhesion or BM retention–related markers (CXCL12, DCN, and TGM2) is reduced or lost at advanced stages of multiple myeloma, which could enhance dissemination and reduce retention in the BM microenvironment." (PMID 38598843, 2024).
Myocardial fibrosis (4 papers, 2020 to 2026). "Tgm2–/–/F13a1–/– mice also develop red blood cell extravasation and myocardial fibrosis, whereas altered fibronectin metabolism was noted in a separate cohort of Tgm2–/–/F13a1–/– mice." (PMID 34617062, 2021). "Contrary to expectation, 3/30 Apoe/F13a1 double knockout mice and 20/28 Apoe/Tgm2/F13a1 triple knockout mice showed myocardial fibrosis (p < 0.0001)." (PMID 31874419, 2020). "Collectively, these data reveal that collagen histaminylation limits TGM2-dependent crosslinking, softens the extracellular matrix, and inhibits the PIEZO1/ITGB1 axis, thereby mitigating myocardial fibrosis after AMI." (PMID 42270610, 2026). "Histaminylation is a newly discovered monoaminylation catalyzed by transglutaminase 2 (TGM2), and its role in myocardial fibrosis has not yet been elucidated." (PMID 42270610, 2026).
pancreatic ductal adenocarcinoma (4 papers, 2020 to 2023). An infiltrating adenocarcinoma that arises from the epithelial cells of the pancreas. "Moreover, PKC has also been suggested to block autophagy in pancreatic ductal carcinoma cells through the activation of tissue transglutaminase 265,66." (PMID 31996710, 2020).
airway hyperresponsiveness (3 papers, 2020 to 2021). "Methacholine-induced airway hyperresponsiveness (AHR) was significantly decreased in the mice with Tgm2-deficient Th17 cells compared to the mice with Tgm2-sufficient WT Th17 cells." (PMID 32793209, 2020).
allergic conjunctivitis (3 papers, 2013 to 2023). "While TGM2 inhibition was shown to be an effective component of a combination therapy against allergic conjunctivitis in a guinea pig model, no studies have been conducted investigating the effect of TGM2 inhibition on corneal wound healing or on the development of cornea haze and scarring." (PMID 36470430, 2023).
clear cell renal cell carcinoma (3 papers, 2020 to 2025). "TGM2 expression is increased in renal clear cell carcinoma compared to normal tissue and forms part of an ECM signature that is significantly associated with overall patient survival." (PMID 36765657, 2023).
cognitive deficits (3 papers, 2023 to 2025). "Deletion of microglial Tgm2 causes impaired synaptic pruning, reduced anxiety and increased cognitive deficits in mice." (PMID 36878712, 2023).
IgA nephropathy (3 papers, 2021 to 2023). "Transglutaminase 2 (TGase2) has been shown to contribute to the mesangial IgA1 deposition in a humanized mouse model of IgA nephropathy (IgAN), but the mechanism is not fully understood." (PMID 37811653, 2023).
kidney tumor (3 papers, 2017 to 2024). "Specifically, the transcript expressions of AKR1C1, S100A2, PLAU, SLC3A2, TBC1D2, and WIZ were decreased, while expressions of TGM2, SLC7A5, and NMI were increased in renal tumors when compared with non-tumorous control samples." (PMID 29272308, 2017).
lung disease (3 papers, 2015 to 2021). "Of the transglutaminases, largely transglutaminase 2 (Tgm2; also called tissue transglutaminase, tTG) has been studied in lung disease and was reported to be expressed in fibroblasts, as well as epithelial, endothelial, and smooth muscle cells." (PMID 26779482, 2015).